RNU6-184P (RNA, U6 small nuclear 184, pseudogene)
Gene: Small nuclear RNA gene on chromosome Y (16,336,283 to 16,336,389, reverse strand). Ensembl gene ENSG00000252323.
Homologues: Orthologues: dog U6 (75% identical). Paralogues in human: RNU6-109P (100% identical), RNU6-1145P (87% identical), RNU6-116P (86% identical), RNU6-1316P (86% identical), RNU6-211P (86% identical), RNU6-310P (86% identical), RNU6-434P (86% identical), RNU6-348P (85% identical), RNU6-38P (85% identical), RNU6-393P (85% identical), RNU6-47P (85% identical), RNU6-698P (85% identical), and 1288 more.